UCP2 (uncoupling protein 2)
Diseases named in the same sentence as UCP2 in open-access papers (continued):
Sharing a sentence is not in itself a finding about the gene and the disease.
Hepatic steatosis (25 papers, 2010 to 2025). Steatosis is a term used to denote lipid accumulation within hepatocytes. "Ar functions as a steroid‐hormone activated transcription factor (Jänne & Shan, 1991), while an upregulation of Ucp2 is associated with fatty liver." (PMID 33991450, 2021). "Uncoupling protein 2 (UCP2), which uncouples mitochondrial oxidative phosphorylation and thus depletes intracellular ATP, has been associated with hepatic steatosis." (PMID 24086674, 2013). "Several studies have demonstrated that hepatic steatosis is associated with increased expression of UCP2 expression." (PMID 23151243, 2012). "However, other studies have demonstrated that UCP2 deficiency caused diminished hepatic utilization and fatty acid clearance and thus it can lead to liver steatosis." (PMID 31035507, 2019). "However, other studies have demonstrated that UCP2 deficiency caused diminished hepatic utilization and fatty acid clearance and thus may lead to liver steatosis." (PMID 28696376, 2017). "Geniposide, a natural inhibitor of UCP2, has been shown to ameliorate hepatic steatosis by blocking UCP2-mediated proton leakage and increasing the mitochondrial membrane potential and ATP synthesis." (PMID 40487402, 2025). "In our study, UCP2 acted as a negative regulator of the mitochondrial function after hepatic steatosis in obese mice." (PMID 34960036, 2021). "At the molecular level, losartan only significantly decreased FAT/CD36 and FAS mRNA together with UCP2 mRNA, but these effects appear insufficient to impact hepatic steatosis or ATP content respectively." (PMID 28231800, 2017). "Excess fat plays a central role in the pathogenesis of hepatic steatosis, and that the effects of excess fat are mediated by PPARs and UCP2 overexpression." (PMID 24086674, 2013). "We showed that nutrient excess in the form of high PA medium resulted in a rapid development of hepatic steatosis that was enhanced by inhibiting UCP2 with genipin." (PMID 23151243, 2012). "In conclusion, the present results demonstrate that UCP2 plays a protective role in free FA-induced hepatic steatosis." (PMID 23151243, 2012). "The present study demonstrates that the tempol, a well-known antioxidant, blocks UCP2 inhibition mediated hepatic steatosis." (PMID 23151243, 2012). "In this study, we assessed the role of UCP2 in regulating ROS production in cultured hepatocytes under the condition of FA treatment and established a critical role of UCP2 in the pathogenesis of hepatic steatosis." (PMID 23151243, 2012). "The adipocyte-derived hormone adiponectin elicits protective functions against fatty liver diseases and hepatic injuries at least in part by stimulating the expression of a mitochondrial inner membrane transporter, uncoupling protein 2 (UCP2)." (PMID 22359684, 2012). "The reduction of hepatic uncoupling protein 2 (Ucp2) gene expression may play a role, since it is thought to play a role in attenuating fatty liver disease in rats." (PMID 35409415, 2022). "In this study, we addressed the hypothesis that excess fat plays a central role in the pathogenesis of hepatic steatosis resulting from the overexpression of PPARα, PPARγ, and UCP2." (PMID 24086674, 2013). "The present study shows that inhibition of UCP2 accelerates hepatic steatosis, indicating that UCP2 might play a compensatory protective role in PA-induced hepatic fat deposition." (PMID 23151243, 2012). "Although the detailed physiological functions of UCP2 remain to be elucidated, it has been suggested that increased expression of UCP2 may help to prevent the development of hepatic steatosis and steatohepatitis." (PMID 22359684, 2012). "Furthermore, palmitoleic acid (C16:1n-7) especially, but other fatty acids as well, activate uncoupling protein 2, which may lead to hepatic steatosis." (PMID 28750643, 2017). "Therefore, we hypothesized that UCP2 might regulate hepatic steatosis though a ROS-dependent pathway." (PMID 23151243, 2012).
Hepatic steatosis (continued). "Thus, UCP2 might be involved in hepatic steatosis via regulating ROS production in the process of excess FA oxidation." (PMID 23151243, 2012). "We hypothesized that UCP2 might regulate hepatic steatosis via suppressing oxidative stress." (PMID 23151243, 2012). "AT1 receptor activation leads to steatosis via decreased UCP2 in a rat model with metabolic syndrome, and the deletion of AT1 receptor reduces hepatic steatosis." (PMID 28101297, 2016). "In the present study GhrR KO mice fed a HFD showed significantly reduced UCP2 expression relative to HFD-fed WT mice, consistent with the decreased hepatic steatosis in HFD-fed GhrR KO mice." (PMID 21211044, 2011). "BPA exacerbated hepatic steatosis in the OVX HBPA group, elevating lipid/collagen deposition with reduced Mttp mRNA and upregulated β-oxidation (Acox1, Acadvl), mitochondrial uncoupling (Ucp2), ER stress (Hyou1, Atf6), and liver injury (Tgfb1, Casp8) genes." (PMID 40475995, 2025). "The hepatoprotective properties of genipin may also be based on the action of uncoupling protein 2 (UCP2), mitochondria quality regulation, anti-fibrinogenic activity, and amelioration of hepatic steatosis." (PMID 35055094, 2022). "Normal hepatocytes do not endogenously express Ucp2, which is found primarily in Kupffer cells where it is believed to alleviate hepatic steatosis through reduction of hepatocellular fat accumulation Baffy, 2005)." (PMID 33991450, 2021). "To verify if SEM may protect mice from hepatic steatosis through its antioxidant activity, we analyzed the expression of the enzymes CYP2E1 and NOX2 as well as of the uncoupling protein UCP2, which are all importantly involved in oxidative stress generation." (PMID 34960036, 2021). "However, TUDCA did not reduce the expression of Pparg, which is a critical transcription factor in development of hepatic steatosis in ob/ob mice, and its direct target genes (e.g., Cidec, Cd36, and Ucp2), suggesting that the TUDCA effect in improving hepatic steatosis is Pparg-independent." (PMID 21079772, 2010).
Hypertension (23 papers, 2007 to 2025). The presence of chronic increased pressure in the systemic arterial system. "A common polymorphism of the UCP2 gene was associated with hypertension in a Japanese population, and with hypertension and obesity in Caucasians." (PMID 20003216, 2009). "UCP2 knockdown by renal subcapsular infusion of a siRNA attenuates hypertension and increases serum NO metabolite levels in these mice." (PMID 33574248, 2021). "Mice null for the redox-sensitive chaperone DJ-1 exhibit hypertension and an upregulation of renal UCP2 expression." (PMID 33574248, 2021). "In SHRs, a RAAS-driven model of essential hypertension, an upregulation of cardiac UCP-2 expression has already been described." (PMID 32120777, 2020). "These transgenic mice are protected against salt-induced hypertension, in line with what has been found in Ucp2-/- mice, suggesting that UCP2 plays a significant part in the regulation of vascular salt sensitivity." (PMID 30116205, 2018). "Using the Ucp2-/- mice, we found that Ucp2 ablation augments high salt diet-induced hypertension and vascular dysfunction." (PMID 30116205, 2018). "Ucp2-/- further raises the superoxide level and attenuates nitric oxide-dependent dilatation of resistance arteries, thus propagating hypertension." (PMID 30116205, 2018). "A tight link exists also between UCP2 and vascular damage in hypertensive disease, particularly in the presence of excess salt intake." (PMID 29163755, 2017). "The early significant reduced expression of the antioxidant AMPK/PPARα/UCP2 pathway that progressed throughout lifetime may contribute to explain higher predisposition of SHRSP to oxidative stress dependent target organ damage in the context of severe hypertension." (PMID 26023797, 2015). "Recently, the role of UCP2 in mediating the endothelial protective effects conferred by a dipeptidyl-4 inhibitor (sitagliptin) in hypertension was reported." (PMID 25561233, 2014). "Our data suggest the existence of central mechanisms that may protect against hypertension-induced organ damage independently of BP, and strengthen the suitability of strategies aimed at enhancing UCP2 expression for the treatment of hypertensive damage." (PMID 32560241, 2020). "Therefore, we analyzed the time-dependent regulation of UCP-2 und Glut-4 in a model of essential hypertension (spontaneously hypertensive rats, SHR)." (PMID 32120777, 2020). "Moreover, a striking downregulation of UCP2 gene and protein expression was found in relation to both hypertension and ageing in the brain, heart, and kidneys of the SHRSP, but not of the SHRSR." (PMID 29163755, 2017). "It has been suggested that an impairment of the protective role of UCP2 may also contribute to hypertension development." (PMID 27594970, 2016). "Due to its wide expression throughout the body, UCP2 may represent an attractive target to preserve the cardiovascular system from both hypertension- and age-related damage as well as to extend lifespan." (PMID 26023797, 2015). "The present study demonstrates for the first time a remarkably different modulation of UCP2 and of all components of UCP2 upstream regulatory pathway along with hypertension development and aging in all target organs of two closely related spontaneously hypertensive rat strains." (PMID 26023797, 2015). "The inverse association between UCP2 expression levels in PBC and uric acid levels is also of interest regarding the relevance of uric acid levels in relation to cardiometabolic risk factors, particularly high blood pressure and elevated insulin and triglycerides." (PMID 31064394, 2019). "To further dissect the cell types important in UCP2 inhibition-induced hypertension, we generated transgenic mice with vascular smooth muscle-specific overexpression of UCP2 protein by expressing exogenous smooth muscle myosin heavy chain promoter driven human UCP2 gene." (PMID 30116205, 2018).
Hypertension (continued). "We performed the present study to test the hypothesis that expression of UCP2 and of its upstream regulatory pathway could be differently modulated in relation to hypertension development and aging in the brain, as well as in the kidneys and heart, of SHRSP as compared to its related control strain." (PMID 26023797, 2015). "We also examine the interactions of UCP2/UCP3 with adiposity and hypertension for prediabetes and T2DM." (PMID 29529994, 2018). "Restoring UCP2 expression levels, as observed under the Brassica oleracea sprouts extract, appears a critical step to prevent TOD development in hypertension." (PMID 27594970, 2016). "Several findings provide evidence that UCP2 is directly involved in the development of cerebral ischemic damage, independent of hypertension." (PMID 29163755, 2017). "A similar striking differential modulation, that is suppression of UCP2 gene and protein expression, was found in relation to both hypertension and aging in the brain, heart, and kidneys of SHRSP but not of SHRSR." (PMID 27594970, 2016). "Therefore, an important finding of this study is that hypertension alone does not induce a nonreversible effect on UCP-2 and Glut-4 expression." (PMID 32120777, 2020). "Tests of association for additional traits (such as hypertension and coagulation factors) that were not part of our a priori hypotheses for either UCP1 or UCP2 were conducted during automated analytical procedures." (PMID 17397545, 2007). "At 2 months of age a significant down-regulation of UCP2 expression at both mRNA and protein levels was found, along with reduced protein expression of all components of UCP2 regulatory pathway, in tissues of SHRSP but not of SHRSR, that progressed with hypertension development and aging." (PMID 26023797, 2015).
endothelial dysfunction (22 papers, 2012 to 2025). In vascular diseases, endothelial dysfunction is a systemic pathological state of the endothelium (the inner lining of blood vessels) and can be broadly defined as an imbalance between vasodilating and vasoconstricting substances produced by (or acting on) the endothelium. "Lastly, we determined that exercise training rescued UCP2 deficiency-mediated endothelial dysfunction in coronary arterioles of ApoE KO via down-regulation of ROS by means of up-regulating UCP2 expressions." (PMID 34326395, 2021). "A more recent study showed similar result that loss of UCP2 exacerbates endothelial dysfunction of coronary arteries from mice on HFD." (PMID 30116205, 2018). "The knockdown of UCP2 in mice fed a high-fat diet has been shown to cause a reduction in antioxidant capacity, endothelial dysfunction, and atherosclerotic deterioration." (PMID 27417103, 2016). "UCP2 deficient mice displayed significant endothelial dysfunction, increase in ROS production and severe atherosclerotic lesions." (PMID 23185428, 2012). "In any case, knockdown of UCP2 in high fat fed mice causes endothelial dysfunction and aggravation of atherosclerosis, whereas its overexpression decreases ROS production and endothelin-1 gene expression while increasing eNOS levels." (PMID 22382745, 2012). "Our findings suggest that exercise training could attenuate UCP2 deficiency-mediated endothelial dysfunction possibly through the elevation of UCP2 expression." (PMID 34326395, 2021). "Though the molecular functions of UCP2/3 are still a matter of debate, these proteins might represent promising candidates for therapeutic interventions in endothelial dysfunction caused by hyperlipidemia." (PMID 22382745, 2012). "In this study, we observed that miR‐497‐5p‐mediated inflammatory endothelial dysfunction in ox‐LDL‐stimulated HUVECs was attenuated following UCP2 overexpression, and confirmed that UCP2 was a direct target gene of miR‐497‐5p." (PMID 40391195, 2025). "UCP2 is a mitochondrial membrane protein and wildly expressed among organs, and overexpression of UCP2 protected against endothelial dysfunction of vessels through reducing ROS production followed by increasing nitric oxide (NO) bioavailability." (PMID 33762949, 2021). "Routine exercise alleviates endothelial dysfunction in atherosclerotic coronary arterioles in an eNOS, UCP2, and ER stress signaling specific manner, and resulting in reduced TXNIP/NLRP3 inflammasome activity and oxidative stress." (PMID 34326395, 2021). "Our aim was to understand how exercise affects ER stress and UCP2 activation, and how that relates to endothelial dysfunction in an atherosclerotic murine model." (PMID 34326395, 2021). "UCP2, in turn, ameliorated endothelial dysfunction by reducing the production of mitochondria-derived ROS and increasing NO release." (PMID 32471282, 2020). "Overexpression of uncoupling protein 2, a mitochondrial modulator that has protective effects against endothelial dysfunction, has also been demonstrated to inhibit apoptosis and decrease ROS levels in human umbilical vein endothelial cells." (PMID 30373222, 2018). "It has been shown that exercise training alleviates endothelium-dependent vasodilation via an increase in UCP-2 expression, i.e., chronic exercise training ameliorated ACh-induced endothelial dysfunction with the elevated UCP-2 expression." (PMID 29784903, 2018). "Uncoupling protein 2, a critical regulator of mitochondrial-derived ROS release, has been shown to attenuate the endothelial dysfunction by increasing NO bioavailability and inhibiting ROS production in diabetic mice." (PMID 24886224, 2014). "Second, TRPV1 activation by capsaicin ameliorated high-glucose-induced endothelial dysfunction in a UCP2-dependent manner." (PMID 23607427, 2013). "Conversely, UCP2-deficient mice exhibited marked endothelial dysfunction following an atherosclerotic diet, even in the absence of other genetic modifications." (PMID 40433124, 2025).
endothelial dysfunction (continued). "Furthermore, the miR‐497‐5p‐mediated NLRP3/caspase‐1/GSDMD pathway and the resulting inflammatory endothelial dysfunction in ox‐LDL‐stimulated HUVECs was also significantly attenuated after UCP2 overexpression." (PMID 40391195, 2025). "And UCP-2 overexpression also ameliorates endothelial dysfunction with increased ROS." (PMID 28683125, 2017). "In agreement with these previous findings, our data demonstrate that ACE2 null mice show a significant decrease in UCP2 mRNA levels in aorta which may directly contribute to the increase in •O2- and decreased •NO bioavailability and, consequently, to endothelial dysfunction." (PMID 27070147, 2016). "Capsaicin administration decreased the production of ROS, restored high-glucose-induced endothelial dysfunction through the activation of TRPV1 and acted in a UCP2-dependent manner in vivo." (PMID 23607427, 2013).